HIRA (histone cell cycle regulator)
Diseases named in the same sentence as HIRA in open-access papers (continued):
Sharing a sentence is not in itself a finding about the gene and the disease.
cancer (13 papers, 2015 to 2026). A tumor composed of atypical neoplastic, often pleomorphic cells that invade other tissues. "Using the KEGG database, we identified several androgen-regulated pathways that are affected by both AR and HIRA KO, including cancer- and metastasis-associated pathways, as FoxO, TNF, TGF-beta, PI3K-Akt, MAPK and Wnt." (PMID 37638746, 2023). "The top 10 frequently affected cancer-associated genes are HIRA (OG), CSMD1 (TS), CDH13 (TS), PRRX1 (OG), FHIT (TS), MGAM (OG), TBL1XR1 (OG), RHOA (OG), FGF14 (TS), and CNTNAP2 (TS)." (PMID 35013466, 2022). "Similarly, HIRA can compensate for the loss of DAXX/ATRX by depositing H3.3 onto telomeric heterochromatin in alternative lengthening of telomeres (ALT) cancer cells." (PMID 38297159, 2024). "Here, we showed that Atad2 is highly expressed in post-meiotic spermatogenic cells and that in its absence, as in ES cells and in different cancer cells, HIRA accumulates." (PMID 41557467, 2026). "Accordingly, dysregulation of HIRA or DAXX complexes is observed in various types of cancers, such as breast, lung, prostate, colorectal, glioma, pancreatic, leukemia, prostate, gastric, ovarian, and chondrosarcoma." (PMID 38297159, 2024). "This is the first study to report that PHB also participates in the HIRA complex in cancer cells and PHB interacts with HIRA through the linker region of the PHB domain." (PMID 32865342, 2020). "These included several cancer-associated genes such as MKL1, EP300, NF2, and HIC2 and chromatin binding genes BRD1, HIRA, and HDAC10." (PMID 25909290, 2015). "Previous studies have demonstrated roles for the histone chaperones such as HIRA, CHAF1B and the molecular co-chaperone DNAJC9 in preventing CENP-A mislocalization in human cancer cells lines." (PMID 39135477, 2024). "The second most recurrently altered TAD boundary (chr22:19600000–19675000) was flanked by active and low-active TADs, and is adjacent to TADs containing the cancer genes SEPTIN5, DGCR8, and HIRA." (PMID 38758740, 2024). "In human cancer cell lines and in mouse embryonic stem cells, we observed that the KO of ATAD2 leads to an accumulation of HIRA." (PMID 34580178, 2021). "Our parallel studies of ATAD2’s function in distinct models, S. pombe, human cancer cells and mouse ES cells, consistently support that ATAD2 is a critical regulator of histone deposition by FACT and HIRA." (PMID 34580178, 2021). "Among other discoveries, this work showed that in the absence of ATAD2, HIRA becomes trapped on chromatin leading to its accumulation in ES cells, as well as in a variety of cancer cell lines." (PMID 41557467, 2026). "In contrast, IFN stimulation of carcinoma cells (U2OS, SAOS, HeLa, and A549) failed to induce the recruitment of HIRA to PML-NBs, even though these cell types expressed similar levels of HIRA mRNA and protein within the nucleus." (PMID 30901352, 2019). "Interestingly, HIRA’s localization to PML bodies was impaired in several, but not all, cancer cell lines." (PMID 28981850, 2017).
infection (8 papers, 2015 to 2025). The state of being infected such as from the introduction of a foreign agent such as serum, vaccine, antigenic substance or organism. "HIRA also deposits H3.3 onto transcriptionally active chromatin throughout the cell cycle and has been implicated in various pro- and anti-viral responses during infection with other DNA viruses." (PMID 41019635, 2025). "The same study also observed that DEK, a H3.3 chaperone that regulates H3.3 distribution to HIRA and ATRX/DAXX, associated with the viral genome for most of the first 6 h of infection." (PMID 33909709, 2021). "HIRA and an upstream H3 chaperone, ASF1A, have been implicated in H3.3-biased occupation of histones on HSV DNA during lytic infection of HeLa cells." (PMID 33909709, 2021). "When transcription was inhibited globally, we found that only a combinatorial depletion of ATRX/HIRA/ASF1A resulted in a significant decrease in total H3 deposition by 4 h post infection (hpi), suggesting multiple pathways for chromatinizing naked DNA." (PMID 33909709, 2021). "HIRA recruitment to PML-NBs under these infection conditions occurred in a JAK-dependent manner and was significantly impaired during WT HSV-1 infection." (PMID 30901352, 2019). "In contrast to PML, which is a well-characterized substrate of ICP0, western blot analysis of infected whole cell lysates revealed that HIRA protein levels remained stable throughout infection." (PMID 30901352, 2019). "We identify these immune defences to occur at spatiotemporally distinct phases of infection, highlighting a critical role for HIRA in the regulation of multiple phases of host immunity in response to pathogen invasion." (PMID 30901352, 2019). "Taken together, these data suggest a role for HIRA at PML-NBs as a component of the host innate immune response to prime cells for imminent infection." (PMID 30901352, 2019). "Recent studies have reported that HIRA accumulates at PML-NBs in response to infection with replication-defective herpesviruses (HSV-1 and HCMV)." (PMID 30901352, 2019). "We therefore identify that virus-induced cytokine signalling cascades to play an important role in the spatiotemporal localization of HIRA at PML-NBs during infection of normal diploid cells." (PMID 30901352, 2019). "Replication-defective herpesviruses promote the activation of PRRs that induce innate immune defences and cytokine secretion, which likely accounts for the stable localization of HIRA at PML-NBs observed under replication-defective infection conditions." (PMID 30901352, 2019). "The accumulation of HIRA in PML NBs following infection by HSV-1 has recently been suggested to be part of an interferon-induced antiviral mechanism." (PMID 30235352, 2018). "In human fetal lung fibroblasts (IMR90), HIRA localized to PML bodies in response to infection with UVHCMV or HSV in1318." (PMID 28981850, 2017). "Nevertheless, our observations are in contrast with the stable recruitment phenotypes reported for HIRA at PML-NBs in response to infection with replication-defective herpesviruses at 2–6 days post-infection (; discussed further below) or IFN stimulation 8–24 hours post-treatment." (PMID 30901352, 2019). "Under replication-competent infection conditions, our transcriptomic and infection biology analysis clearly demonstrate that HIRA plays important roles in the induction of innate immune defences and ISG expression during HSV-1 infection that correlates with its enrichment of localization at PML-NBs." (PMID 30901352, 2019). "Notably, exogenous cytokine stimulation (IFN-β and IFN-γ) can induce HIRA localization to PML-NBs independently of infection, supporting a role for HIRA at PML-NBs as a component of the innate immune response." (PMID 30901352, 2019). "Under productive infection conditions, HIRA recruitment to infecting viral genomes could only be observed following the saturation of PML-NB host defences and the onset of ΔICP0 HSV-1 DNA replication by 6 hpi." (PMID 30901352, 2019).
infection (continued). "Collectively, our data demonstrate that HIRA recruitment to PML-NBs in the context of lytic replication in diploid cells represents a sequential step in the paracrine activation of innate immune defences to prime cells for imminent infection." (PMID 30901352, 2019). "Furthermore, we found that many of IFIX interactions were lost following infection, including PML and its associated proteins (DAXX, ATRX, HIRA, etc.)." (PMID 25665578, 2015). "Previous studies have reported that HIRA and ASF1A promote H3.3 and total H3 occupation, respectively, on the HSV genome during early lytic infection in HeLa cells." (PMID 33909709, 2021). "These intracellular host defences are antagonized by the HSV-1 ubiquitin ligase ICP0, which disrupts the stable recruitment of HIRA to infecting viral genomes and PML-NBs at spatiotemporally distinct phases of infection." (PMID 30901352, 2019). "We thus investigated the localization of all members of the HIRA complex and found that they co-localized with the latent/quiescent HSV-1 genomes at 2 days post-infection (dpi) in BJ and other human primary cells." (PMID 30235352, 2018). "After infection of primary cells with HSV or CMV, or transient transfection with naked plasmid DNA, HIRA re-localizes to PML bodies, sites of cellular anti-viral activity." (PMID 28981850, 2017). "We conclude that HIRA does not stably colocalize with input vDNA or PML-NBs under infection conditions in which key intrinsic PML-NB restriction factors (PML, Sp100, Daxx, and ATRX;) rapidly entrap and silence vDNA following its nuclear entry." (PMID 30901352, 2019). "We therefore sought to investigate the spatiotemporal kinetics of HIRA localization to infecting HSV-1 genomes and PML-NBs in the sequential regulation of intrinsic and innate immune defences under productive lytic infection conditions pertinent to a clinical setting." (PMID 30901352, 2019). "Fourth, while HIRA is not required for IFN inducible gene expression, we observed an increase in virus yield from infected cells in absence of HIRA, after infection with HSV lacking the viral transcriptional activator ICP0." (PMID 28981850, 2017). "However, the stable localization of HIRA at PML-NBs was only observed at comparatively late times post-infection (2–6 days;), which is atypical of intrinsic PML-NB host factors that silence viral gene expression from the outset of nuclear infection." (PMID 30901352, 2019). "Nor can we discount a repressive role for HIRA at PML-NBs in other infection contexts, for example during the establishment of viral latency in sensory neurones, where the presence or absence of specific viral or cellular factors may influence the mechanism of viral chromatin assembly and silencing." (PMID 30901352, 2019). "As nuclear infection in and of itself was not sufficient to induce the stable recruitment of HIRA to vDNA or PML-NBs by 180 mpi, we next evaluated HIRA localization at PML-NBs under infection conditions that enabled the induction of innate immune defences." (PMID 30901352, 2019). "Two members of the HIRA complex, HIRA and ASF1a, were previously shown to be involved in H3.3-dependent chromatinization of HSV-1 genomes at early times after infection in non-neuronal and non-primary cells favoring the onset of the lytic cycle." (PMID 30235352, 2018). "This is supported by reports that HIRA and ASF1A promote histone occupation on HSV DNA during the first few hours of infection but do not appear to be restrictive during this same period of time." (PMID 30465651, 2018). "While HIRA depletion did not significantly influence the levels of WT HSV-1 replication under low MOI conditions (0.0005 PFU/cell), we could observe diminished levels of WT HSV-1 gene expression at early time points post-infection (2–6 hpi)." (PMID 30901352, 2019).
tumor (8 papers, 2010 to 2024). "Several reports have implicated HIRA in cell cycle arrest, senescence and tumor suppression." (PMID 26935106, 2016). "Although its role in cancer is still poorly characterized, HIRA has been shown to suppress oncogene-induced neoplasia by activating a senescence phenotype in a mouse model of skin cancer and to block cell cycle progression in S phase in osteosarcoma cells." (PMID 36269833, 2022). "Notably, HIRA is known to regulate the epigenetic landscape of senescent cells, to suppress neoplasia, and, more generally, to play a role in tumorigenesis." (PMID 36269833, 2022). "In contrast to development processes, altered functions of HIRA and DAXX as H3.3 histone chaperones have distinct consequences in tumor development and progression." (PMID 38297159, 2024). "A similar result was obtained by analysing the GSE121248 and GSE33006 datasets from the GEO database, and nearly all H3–H4 histone chaperones were significantly overexpressed in tumor tissues, except for APLF, HIRA and NASP." (PMID 38561384, 2024). "Exploring the function of H3.3 in PC (TCGA and the Human Protein Atlas), we found that expression of two HIRA complex components, proteins HIRA and UBN1, is increased in tumor compared to normal prostate tissue." (PMID 37638746, 2023). "In contrast to the oncogenic consequences of HIRA-mediated H3.3 deposition, HIRA can function as a tumor suppressor independent of its chaperone activity." (PMID 38297159, 2024). "In carcinoma cell lines, the ERK2 signaling reduces the levels of H3.1/H3.2 by suppressing CHAF1B transcription, thus creating the “space” for gap-filling with H3.3, leading to a HIRA-dependent H3.3 enrichment at the promoter of EMT, resulting in tumor progression and metastasis formation." (PMID 35087762, 2021).
HIRA also shares sentences with these, for which no sentence is quoted: lung carcinoma (2 papers); thalassemia (2); alpha thalassemia-X-linked intellectual disability syndrome (1); Alzheimer disease (1); cardiac hypertrophy (1); cardiomyopathy (1); coronary heart disease (1); Fanconi anemia (1); hereditary leiomyomatosis (1); ichthyosis (1); insulin-dependent diabetes (1); lymphocytopenia (1); melanoma (1); mental retardation (1); mucosal (1); neuropathy (1); Opitz G/BBB syndrome (1); osteoporosis (1); Parkinson disease (1); periodontitis (1); prostate adenocarcinoma (1); rheumatoid arthritis (1); Thrombocytopenia (1).